SMAD7 (SMAD family member 7)
Diseases named in the same sentence as SMAD7 in open-access papers (continued):
Sharing a sentence is not in itself a finding about the gene and the disease.
liver fibrosis (continued). "Previous studies have shown that liver fibrosis is involved in the regulation of the deposition of ECM by a complex network of signaling pathways, and we have investigated CGA could regulate liver firbosis through IL-13/miR-21/Smad7 signaling way." (PMID 29311932, 2017). "Compared with the blank control group, the gene expression of Smad2 and Smad3 in the TGF-β1 experimental group was increased while Smad7 was decreased, indicating that TGF-β/Smad pathway may be involved in the process of excessive activation of HSC and hepatic fibrosis." (PMID 27990439, 2016). "However, whether CGA can inhibit liver fibrosis through the miR-21-regulated TGF-β1/Smad7 signaling pathway has not been studied." (PMID 29311932, 2017). "However, there are no reports on Smad7 in human liver fibrosis." (PMID 19878580, 2009). "Smad7 is a negative feedback regulator of TGF-β signaling, and increasing Smad7 expression can delay liver fibrosis." (PMID 41154556, 2025). "The absence of SMAD7 was widely noted in HCC tissues compared to background liver tissue, and a pronounced decline in SMAD7 levels in rat models with advanced liver fibrosis and cirrhosis was found as compared to normal rat liver tissue." (PMID 33763375, 2021). "In this signaling pathway, Smad7 is an inhibitory Smad, a negative feedback regulator in the TGF-β signaling pathway that can attenuate TGF-β1 induced HSCs activation and improve liver fibrosis." (PMID 35711641, 2022).
breast carcinoma (72 papers, 2007 to 2025). "The expression of SMAD2 and SMAD7 is associated with outcomes in breast cancer patients, for downregulated SMAD2 and SMAD7 promote breast cancer metastasis." (PMID 35461253, 2022). "This study was performed to investigate the relationship between rs6715345 and rs4939827 polymorphisms of miR-375 and SMAD-7 genes respectively in women with breast cancer as well as in healthy women." (PMID 32856881, 2020). "In conclusion, this study indicated that single-nucleotide rs4939827 polymorphism of the SMAD-7 gene is associated with developing breast cancer." (PMID 32856881, 2020). "Germline P/LP variants in SMAD7, a gene associated with colorectal and breast cancers, were found in six of our high-grade glioma patients." (PMID 32371905, 2020). "Based on our findings, rs4939827 polymorphism of the SMAD-7 gene is significantly linked to the risk of developing breast cancer." (PMID 32856881, 2020). "The results suggest that the rs4939827 polymorphism of the SMAD7 gene can lead to an increased risk of incidence of breast cancer in the southeastern population in Iran." (PMID 32856881, 2020). "In breast cancer, SMAD7 is destabilized by loss of expression of specific deubiquitinases, augmenting TGF-β1 signaling and the acquisition of metastatic behavior." (PMID 29799477, 2018). "We also elucidate the underlying mechanism and show that OTUD1 empowers SMAD7 to inhibit TGF-β signaling in breast cancer metastasis." (PMID 29235476, 2017). "Here, the authors show that OTUD1 suppresses metastasis by antagonizing the TGF-β pathway via the deubiquitination of SMAD7, and its loss correlates with poor prognosis in breast cancer." (PMID 29235476, 2017). "Hong and colleagues showed that over-expression of Smad7 sensitized MCF7 breast cancer cells to TNF-induced cell death and associated this effect with inhibition of expression of antiapoptotic NF-κB target genes." (PMID 24317436, 2013). "A previous retrospective study showed that SMAD7 overexpression is linked with a reduced incidence of bone metastases from melanoma and breast cancer." (PMID 23284751, 2012). "However, the rs4939827 polymorphism of the SMAD7 gene was significantly linked to the risk of developing breast cancer in the southeastern population in Iran (p<0.05)." (PMID 32856881, 2020). "Confirming these observations, SMAD7 overexpression or SB431542 treatment nearly abolished breast cancer cell migration otherwise induced by CAF‐sEVs." (PMID 40091448, 2025). "All three microRNAs were upregulated and repressed NEDD4L, EP300, and SMAD7 in breast cancer, influencing epithelial–mesenchymal transition, tumoral transformation, and therapy response." (PMID 40943553, 2025). "Concurrently, a significant reduction in SMAD7 expression removes inhibitory control in the TGFβ pathway, a phenomenon that is particularly evident in more aggressive breast cancer types." (PMID 39337574, 2024). "At the same time, a significant decrease in SMAD7 expression removes regulatory breaks in the TGFβ pathway, which is particularly evident in more aggressive types of breast cancer." (PMID 39337574, 2024). "In our study, SMAD7 expression significantly decreased in all types of breast cancer, with the greatest decrease observed in TNBC." (PMID 39337574, 2024). "RNF12 was also found to interact with and target Smad7 for degradation to promote TGF‐β‐driven metastasis in breast cancer." (PMID 37132043, 2023). "SMAD7, a suppressor molecule of the TGF-β pathway, is strongly associated with the prognosis of breast cancer patients." (PMID 37685308, 2023). "OTUD1 acts as a tumor suppressor in breast cancer by mitigating TGF-β-induced pro-oncogenic responses by increasing SMAD7 levels." (PMID 35013159, 2022). "The top three focused molecules are TGF-beta, NF-kappa-B, and beta-catenin, and the most common diseases involved in studies on SMAD7 include breast cancer, colorectal cancer, and hepatocellular carcinoma." (PMID 35252215, 2021).
breast carcinoma (continued). "miRNA-497 acts as a direct negative regulator of SMAD7 expression, inhibiting breast cancer cell growth and invasiveness." (PMID 34059951, 2021). "Taken together, all the results indicated that SMAD7 mediated the effect of ARHGAP5-AS1 on breast cancer cell migration." (PMID 34370213, 2021). "SET domain bifurcated 1 (SETDB1) is a histone methyltransferase that regulates the expression of Smad7 in breast cancer (BRC) cells." (PMID 34059951, 2021). "Gdf10 has been reported to act as a tumor suppressor in mammary epithelial cells that limits proliferation and suppresses epithelial-mesenchymal transition in breast cancer via upregulation of Smad7." (PMID 34104113, 2021). "In this context, Smad7 has been shown to inhibit the activation of β-catenin and increase the expression of β-catenin and E-cadherin in breast cancer and hepatocellular carcinoma, respectively." (PMID 34059951, 2021). "MTA1 regulates Smad7 expression by enriching the SMAD7 promoter and is involved in the tumorigenesis and metastasis of breast cancer." (PMID 34059951, 2021). "OUT domain-containing protein 1 (OTUD1) was found to inhibit breast cancer stem-cell traits and metastasis via deubiquitination of Smad7." (PMID 34059951, 2021). "A strong relationship between miR‐497 and Smad7 has been recorded in the literature that the expression of miR‐497 was inversely correlated with the Smad7 expression in breast cancer tissues and oral squamous cell carcinoma." (PMID 32975015, 2020). "This study has been performed to investigate the relationship between polymorphisms of rs6715345 of miR-375 gene and rs4939827 of the SMAD7 gene and development of breast cancer in a population in southeastern Iran." (PMID 32856881, 2020). "It has been proposed that breast cancer cells can upregulate Smad7, which in turn leads to decreased ERK signaling and diminished expression of CTGF." (PMID 31454892, 2019). "Recent studies with 2MeOE2 treatment have shown that it induces JNK, Erk-1/2 and p38 activation in breast cancer cells, stabilizes SMAD7 and induces p38-MAPK mediated apoptosis in prostate cancer and retinoblastoma cells." (PMID 31128594, 2019). "A computational model of non-linear regression is shown, based on deep neural networks that predict the regulation given by the miRNA target transcripts mRNA coding for Smad7 protein in patients with breast cancer, with R2 of 0.99 is shown and MSE of 0.00001." (PMID 30594253, 2018). "The purpose of this work is to identify a miRNAs profile that regulates the expression of the mRNA coding for Smad7 in breast cancer using the data from patients with breast cancer obtained from the Cancer Genome Atlas Project." (PMID 30594253, 2018). "Then, we analysed the consequences of miR-182 and SMAD7 overexpression in breast cancer bone metastasis in vivo." (PMID 27996004, 2016). "To further investigate the clinical relevance of SMAD7 suppression by miR-182, we examined a cohort (n=24) of breast cancer clinical samples collected from Qilu Hospital by q-PCR of miR-182 and IHC staining of SMAD7." (PMID 27996004, 2016). "miR-106b has been shown to participate in activation of the TGF-β/Smad signaling pathway by inhibiting Smad7 protein expression to intensify the epithelial mesenchymal transition (EMT) in breast cancer cells." (PMID 26769181, 2016). "Previous study found that miR-106b enhanced the migration in breast cancer cells by activating the TGF-β/Smad signaling pathway via degradation of Smad7." (PMID 26769181, 2016). "We therefore conclude that breast cancer cells require close contact with fibroblasts in order to upregulate Smad7 which, in turn, leads to decreased ERK signalling resulting in diminished expression of the stromal proteins CCN2 and type I collagen." (PMID 24090133, 2013).
breast carcinoma (continued). "These events are Smad-dependent as the formation of osteolytic lesions in mice by breast cancer, melanoma, and renal carcinoma cells can be blocked by overexpressing the inhibitory Smad7 or a dominant negative TGFβ receptor." (PMID 27340590, 2012). "Blockade of Smad-mediated TGF-β signaling by overexpression of Smad7 in breast cancer cells has been shown to reduce bone metastases." (PMID 22629385, 2012). "Moreover, according to our results, SMAD3 and SMAD7 are predicted targets of miR‐195‐5p, and their altered expression is associated with epithelial‐to‐mesenchymal transition (EMT) in breast carcinoma, as reported in previous studies." (PMID 40548926, 2025). "Moreover, we confirmed the requirement of an active TGF‐β signalling in breast cancer cells by showing that CAF‐induced MCF7 migration is impaired in SMAD7 overexpressing cancer cells and by SB431542 treatment." (PMID 40091448, 2025). "In addition, SMAD3, SMAD6, and SMAD7 were lowly expressed in stage II breast cancer, while SMAD4 and SMAD2 were lowly expressed in stage III cancer." (PMID 38514720, 2024). "In addition, RNF12 interacted with and ubiquitinated SMAD7 to cause its degradation and promote TGF‐β‐induced breast cancer metastasis." (PMID 37132043, 2023). "HDAC inhibitors increase SMAD7 expression in fibroblasts and breast cancer cells." (PMID 35681828, 2022). "This led to SMAD7 protein stabilization and inhibition of breast cancer cell migration." (PMID 36250017, 2022). "It has been reported that ARHGAP5‐AS1 could suppress cell migration through downregulating SMAD7 expression in breast cancer cells." (PMID 36354136, 2022). "NBT mimics of the SMAD7 interaction domain of ARHGAP5-AS1 could have therapeutic potential in breast cancer." (PMID 36250017, 2022). "ARHGAP5-AS1 inhibits breast cancer cell migration via stabilization of SMAD7 protein and could serve as a novel biomarker and a potential target for breast cancer in the future." (PMID 34370213, 2021). "In order to determine whether SMAD7 is involved in the suppression of ARHGAP5-AS1 on breast cancer cell migration, antisense DNA oligos was utilized to knockdown SMAD7 which mimicked knockdown of ARHGAP5-AS1." (PMID 34370213, 2021). "Similarly, OUT domain-containing protein 1 (OTUD1) inhibits breast cancer metastasis by modulating Smad7 deubiquitylation, attenuating the TGF-β-induced oncogene response." (PMID 34059951, 2021). "Defining the actual function of SMAD7 is complicated by its divergent activities in different tumor types; in melanoma and breast cancer, SMAD7 exhibits anti-tumor properties, whereas in skin, colon, pancreas, and endometrial malignancies, SMAD7 acts as a tumor promoter." (PMID 29799477, 2018). "miR-21 promotes the proliferation and invasion of breast cancer cells by suppressing Smad7." (PMID 30594253, 2018). "Thus, OTUD1 represses breast cancer metastasis by mitigating TGF-β-induced pro-oncogenic responses via deubiquitination of SMAD7." (PMID 29235476, 2017). "In the human breast cancer cell lines, we showed that Smad3 binding to known target sites in the promoters of the SMAD7, COL7A1, and SERPINE1 genes in M3 cells was maximal by 1 hour after TGF-β addition, so this time point was selected for the ChIP-chip analysis." (PMID 24890385, 2014). "Finally, Smad7 was suggested to negatively regulate the EGF signaling pathway in breast cancer cells as ectopic Smad7 expression in SKBR3 cells completely abrogated EGF-induced MMP-9 expression." (PMID 24317436, 2013). "MiR-106b could induce epithelial-to-mesenchymal transition (EMT) and a tumor initiating cell phenotype in breast cancer by targeting Smad7 and Six1 and activating TGF-β signaling." (PMID 24040025, 2013).
breast carcinoma (continued). "Although Smad pathway has been shown to mediate the prometastatic function of TGF-β in the development of metastases of breast cancer and melanoma in mouse model, our results provide the first evidence that blockade of Smad pathway by Smad7 in colon cancer cells increases liver metastasis." (PMID 18781153, 2008). "Moreover, endogenous OTUD1 was found to interact with SMAD7 in breast cancer cells." (PMID 29235476, 2017). "Moreover, overexpression of the inhibitory Smad7 impaired mammary carcinoma cell invasion." (PMID 27340590, 2012). "OTUD1 can deubiquitinate SMAD7 to enable SMURF2 binding and subsequent TβRI turnover on the cell surface to increase breast cancer metastasis." (PMID 38351029, 2024). "SMAD4, SMAD2, SMAD3, SMAD7, SMAD1, SMAD6, and SMAD5 showed genetic variation in 1.8%, 1.2%, 1.1%, 0.8%, 0.7%, 0.6%, and 0.5% of patients with breast cancer, respectively." (PMID 38514720, 2024). "While TGF-β-induced miR-182 inhibited SMAD7 to promote EMT, invasion, and distant metastasis of breast cancer cells." (PMID 37127752, 2023). "Other downstream genes of miR-21-5p have also been reported in human diseases, such as SFRP5 in non‐alcoholic steatohepatitis, SMAD7 in lung cancer, PDCD4 in breast cancer, and LIFR in gastric cancer." (PMID 35549815, 2022). "The phosphorylated RNF12 becomes more effective in inducing the ubiquitination and degradation of SMAD7, therefore, enforces TGF-β-induced invasion and metastasis responses in breast cancer cells." (PMID 35013159, 2022). "There were five proteins correlated to breast cancer progression among all ARHGAP5-AS1-interacting proteins, and SMAD7 showed highest fluorescence intensity." (PMID 34370213, 2021). "The regulatory mechanism involves SMAD7, whose expression is regulated by SETDB1, as SETDB1 knockdown upregulated SMAD7 and suppressed metastasis of breast cancer cells." (PMID 34360879, 2021). "“The miR-106b-25 cluster targets Smad7, activates TGF-β signaling, and induces EMT and tumor initiating cell characteristics downstream of Six1 in human breast cancer” was the top highly cited article with 188 citations." (PMID 35252215, 2021). "These miRNAs can also target the TGF-β inhibitor Smad7 to activate the TGF-β signalling and induce EMT and tumour initiating cell characteristics downstream of Six1 in human breast cancer." (PMID 31728016, 2020). "Novel regulators of SMAD7, including OTU domain- containing protein 1 (OTUD1) and ubiquitin-specific protease 26 (USP26), attenuate TGF-β1-mediated aggressive phenotypes in breast cancer." (PMID 29799477, 2018). "USP26 regulates SMAD7 stability, by deubiquitinating SMAD7, mitigating TGF-β1-induced migration and invasion in breast carcinoma cell lines." (PMID 29799477, 2018). "The nominally significant SNPs included colorectal cancer GWAS SNPs in SMAD7, C11orf93, SCG5, and ATF1, and breast cancer SNPs related to CDKN2B-AS1, FGFR2, GDI2, CDYL2." (PMID 29698419, 2018). "The Smad7 protein is negative regulator of the TGF-β signaling pathway, which is upregulated in patients with breast cancer." (PMID 30594253, 2018). "Our results also showed Smad7 as the target of SOX7 and AXIN2 in controlling breast cancer progression through the Wnt/β-catenin signaling pathway." (PMID 27188720, 2016). "Our results also suggested Smad7 to be the target of SOX7 and AXIN2 in controlling breast cancer progression through the Wnt/β-catenin signaling pathway." (PMID 27188720, 2016). "Mir-106 too was described as deeply involved in TGFβ protumorigenic signaling through targeting of SMAD7, in turn inducing EMT in breast cancer, similarly to miR-10b, induced by TGFβ1 and promoting EMT in breast cancer." (PMID 26188123, 2015). "In breast cancer, miR-93 was involved in the epithelial mesenchymal transition (EMT) by inhibiting the expression of Smad7 and activating the TGF-β signalling pathway." (PMID 25578493, 2015).
breast carcinoma (continued). "Papageorgis and co-workers delineated a link between Smad7 and the maintenance of epigenetic silencing of epithelial genes during EMT of breast cancer cells." (PMID 24317436, 2013). "Furthermore, in breast cancer, the BMP4–SMAD7 signalling axis blocks tumour metastasis, and increased levels of BMP4 and SMAD7 predicted improved recurrence-free survival and OS in breast cancer patients." (PMID 37685308, 2023). "This hypothesis was verified by in vitro study given that miRNA-transfected MCF-7 breast cancer cells showed decreased expression of the TGF-β-related proteins such as TGFβRII, SMAD4, and SMAD7 compared to control, in concordance with previous literature." (PMID 30989460, 2019). "Moreover, OTUD1 correlated with the SMAD7 expression in our breast cancer tissue microarray analysis, further corroborating that OTUD1 has an essential role in the control of SMAD7 stability and activity." (PMID 29235476, 2017). "To investigate whether the feedback loop actually takes effect in cancer cells, we treated the breast cancer cell line MCF10AT with the TGFβ1 cytokine in a time course of 6–72 h, and then examined the SMAD7 expression." (PMID 27996004, 2016). "In conclusion, we demonstrate here, for the first time, that SOX7 plays the role of tumor suppressor on β-catenin by targeting Smad7, together with AXIN2 as a portential co-regulator of the Wnt/β-catenin signaling pathway in controlling breast cancer progression." (PMID 27188720, 2016). "In the last step, miRNA microarray analysis was performed to identify differentially expressed miRNAs in each breast cancer subtype, and then it was determined whether they could participate in the regulation of the expression of SMAD3, SMAD4, SMAD5, and SMAD7 selected in previous steps." (PMID 39337574, 2024). "In an orthotopic immunocompromised breast cancer model, overexpression of syndecan‐2 in TASCs significantly enhanced TGFβ signalling (SMAD7, PAI‐1), tumour growth and metastasis, whereas reducing levels of SDC2 in TASCs attenuated TGFβ signalling (SMAD7, PAI‐1, CXCR4), tumour growth and metastasis." (PMID 33152121, 2021). "Having shown that USP26 is induced by RAC1B and that its knockdown decreased SMAD7 protein abundance, it remains to be determined whether in pancreatic carcinoma cells USP26 indeed binds to and deubiquitinates SMAD7 in breast cancer and glioma cells." (PMID 32545415, 2020).